ALB (albumin)
Diseases named in the same sentence as ALB in open-access papers (continued):
Sharing a sentence is not in itself a finding about the gene and the disease.
endothelial dysfunction (continued). "Albumin, although underused in prior prediction models, has been linked to endothelial dysfunction, maternal malnutrition, and fluid imbalance, and its inclusion here emphasizes the interplay between hepatic reserve and vascular integrity in dual-risk pregnancies." (PMID 41341133, 2025). "First, low albumin levels are associated with endothelial dysfunction." (PMID 38396162, 2024). "The increase in urinary albumin, fetuin, and apolipoprotein A1 may all be consequences of a similar underlying mechanism: endothelial dysfunction resulting in a loss of functionality of the glomerular filtration barrier." (PMID 39335603, 2024). "A review of animal studies has shown that hyperinsulinemia and IR may cause kidney damage by increasing albumin excretion, glomerular hyperfiltration, endothelial dysfunction, and incrementing the risk of kidney fibrosis." (PMID 36624389, 2023). "Endothelial abnormalities are more closely associated with increased urine albumin excretion than podocyte injury, suggesting that endothelial dysfunction may play a more critical role in GFB alterations in DN than podocyte damage." (PMID 36139492, 2022). "A low concentration of albumin may lead to endothelial dysfunction and was found to be an independent risk predictor for all-cause mortality at 40 months follow-up in patients with STEMI." (PMID 36012430, 2022). "A possible mechanism for these findings is the secretion of inflammatory factors from central or visceral adipose tissue such as tumor necrosis factor-alpha and interleukin-6 which causes endothelial dysfunction at the glomerular level, resulting in an increase in urine albumin excretion." (PMID 34461808, 2021). "Furthermore, serum albumin is known to be associated with arterial stiffness, inflammation, and endothelial dysfunction." (PMID 33441045, 2021). "Hence, increased urinary albumin excretion as a marker of permanent glomerular/endothelial dysfunction and increased cardiovascular risk has some limitations because it varies depending on systemic inflammatory and hormonal status." (PMID 32758145, 2020). "Furthermore, previous studies have revealed that urinary albumin excretion is associated with endothelial dysfunction of the macrocirculation by using flow-mediated dilation of brachial and coronary arteries." (PMID 31369578, 2019). "This pathway may be the route of albumin transport that causes endothelial dysfunction during dengue virus infection." (PMID 29419739, 2018). "Additionally, it was suggested that albuminuria is associated with increase of albumin and fibrinogen transcapillary escape rate, which reflects widespread vascular damage or endothelial dysfunction." (PMID 26989695, 2016). "Alternatively, endothelial dysfunction may be involved in the mechanism underlying the observed relationship between urinary excretion of albumin and other factors." (PMID 23830507, 2013). "Since endothelial dysfunction is an early step of atherosclerosis, these factors may cause urinary albumin excretion via endothelial damage." (PMID 23830507, 2013). "Low albumin levels may cause atherosclerotic disease through endothelial dysfunction." (PMID 34430169, 2021). "When circulating proteins such as albumin become glycated in the plasma, they stimulate various receptors on endothelial cells of blood vessels (microvascular and macrovascular), leading to endothelial dysfunction." (PMID 41147020, 2025). "Minor urinary albumin signals greater glomerular leakiness, often due to broad endothelial dysfunction central to CVDs." (PMID 41536368, 2025). "Evidence has also described higher concentrations of endothelial dysfunction markers decades postpartum, such as soluble vascular cell adhesion molecule-1, soluble E-selectin, sFlt-1, urinary albumin/creatinine ratio, and high-sensitivity C-reactive protein." (PMID 41375695, 2025).
endothelial dysfunction (continued). "Low albumin levels can contribute to complications, such as endothelial dysfunction and platelet aggregation, potentially leading to coronary artery stenosis." (PMID 40647637, 2025). "Persistent inflammation results in a lower albumin concentration and leads to the deterioration of endothelial dysfunction." (PMID 40572679, 2025). "Low level HRR is often dominated by chronic inflammation and oxidative stress, which further leads to systemic vascular endothelial dysfunction, glomerular filtration barrier damage, and increased urinary albumin excretion rate." (PMID 41323999, 2025). "The reference studies attest that endothelial dysfunction appears from the first stages of renal damage and correlates with disease activity, particularly the degree of proteinuria and serum albumin levels." (PMID 40375997, 2025). "Lastly, increased BUN can lead to endothelial dysfunction, while decreased serum albumin can lead to increased blood viscosity and impaired endothelial function." (PMID 40290308, 2025). "Endothelial dysfunction, an early feature of atherosclerosis, is ameliorated by bilirubin through binding to lipids or albumin in atherosclerotic lesions and scavenging hydroxyl radicals and superoxide anions." (PMID 40612433, 2025). "Firstly, elevated UACR reflects increased urinary albumin excretion, which not only serves as a biomarker for kidney disease but also indicates systemic endothelial dysfunction." (PMID 40416385, 2025). "UA contributes to endothelial dysfunction, inflammation, and thrombus formation, while albumin exhibits anti-inflammatory and antioxidant properties." (PMID 40322371, 2025). "Markers of BBB and Endothelial Dysfunction: The CSF/serum albumin ratio (Qalb) is a classic marker of BBB integrity and is often elevated in VaD." (PMID 41010812, 2025). "IR promotes renal injury through endothelial dysfunction, oxidative stress, low-grade inflammation, and profibrotic signaling, which collectively accelerate glomerular injury and urinary albumin excretion." (PMID 41155790, 2025). "Elevated CRP levels have consistently been linked to increased mortality and adverse cardiovascular events, while lower albumin levels indicate poor nutritional and inflammatory status, endothelial dysfunction, and heightened oxidative stress." (PMID 41515507, 2025). "Activated platelets play a significant role in enhancing coagulation function and inflammation, leading to endothelial dysfunction, increased capillary permeability, renal protein leakage, and the presence of albumin in urine." (PMID 38726343, 2024). "Smoking status was reported to be associated with low serum albumin levels, as reported in the previous studies, and was also a risk factor for PAD, which increased oxidative stress and inflammation and induced endothelial dysfunction." (PMID 38405142, 2024). "Serum albumin lessens endothelial dysfunction by directly inhibiting oxidative stress and inflammatory pathways." (PMID 39364405, 2024). "Albumin 4%, when compared to crystalloids, reduced endothelial dysfunction, inflammation and oxidative stress in a rat endotoxemia model." (PMID 37728777, 2023). "Endothelial dysfunction and hyperinflammation increased vascular permeability and decreased sodium, albumin, and phosphate levels, while elevating CRP, fibrinogen, D-dimers, and proBNP." (PMID 37646033, 2023). "In this study, we aimed to determine endothelial dysfunction and ischemia-modified albumin (IMA) levels in patients diagnosed with erectile dysfunction (ED) and to examine the relationship between these and diabetes disease." (PMID 35585936, 2022). "A decrease in albumin attenuates its function to improve endothelial dysfunction, regulate vascular tone, suppress platelet aggregation, and maintain endothelial permeability." (PMID 36294818, 2022).
endothelial dysfunction (continued). "The link between moderately elevated urine albumin excretion (UAE) and atherosclerosis seems to be inflammation with endothelial dysfunction, leading to increased permeability and leakage of albumin through the vessel wall." (PMID 35614069, 2022). "Microalbuminuria, a urine albumin excretion ranging from 30 to 300 mg/day, is described as a marker of endothelial dysfunction, and glomerular hyperfiltration, and is correlated with the structural and functional integrity of the vasculature." (PMID 35858835, 2022). "Among the possible pathophysiological mechanisms involved in the excretion of albumin, a plasma protein synthesized by the liver, are inflammation, endothelial dysfunction and capillary permeability." (PMID 34475440, 2021). "It is characterized by endothelial dysfunction with albumin influx into the vessel wall and macrophage accumulation in atherosclerotic lesions." (PMID 34681063, 2021). "The endothelial dysfunction is involved in microcirculatory blood flow impairment and associated with vasomotor tone dysregulation, activation of coagulation, and glycocalyx damage, thus, the benefit of the albumin administration within 24 h may owe to its anti-oxidant properties." (PMID 33689042, 2021). "Urinary albumin excretion is currently considered to be a marker of endothelial dysfunction and atherosclerosis; therefore, it is advisable to determine this indicator in both CKD and metabolic disorders." (PMID 33456602, 2020). "Endothelial dysfunction leads to impairment of the endothelial barrier, which results in increased transvascular albumin leakage." (PMID 30765747, 2019). "It is possible that endothelial dysfunction is innate, because increased albumin excretion has been observed in neonates and toddlers with a high variability of individual." (PMID 28575100, 2017). "Endothelial dysfunction, transvascular blood albumin leakage and chronic inflammation due to PM exposure can be considered possible causes of cardiovascular problems." (PMID 28376835, 2017). "An increased level of albuminuria is an indicator of blood albumin leakage due to systemic inflammation and endothelial dysfunction." (PMID 28376835, 2017). "Increased urinary albumin:creatinine ratio (ACR) has been associated with impaired endothelial-dependent vasodilation, a surrogate measure of endothelial dysfunction." (PMID 26215814, 2015). "There is evidence of systemic endothelial dysfunction as measured by urinary albumin:creatinine ratio (ACR) in patients undergoing open AAA repair correlating with outcome from ALI in this setting." (PMID 26215814, 2015). "Microalbuminuria, resulting from leakage of albumin across the glomerular podocyte filtration barrier into the urine, is known to be a marker of generalized endothelial dysfunction." (PMID 24892930, 2014). "These disorders result in endothelial dysfunction and glomerular hypertension and consequently lead to an increase in urinary albumin excretion." (PMID 24265736, 2013). "The mechanism linking endothelial dysfunction, albuminuria and CVD is that endothelial dysfunction leads to increased vascular permeability and glomerular albumin leakage." (PMID 23469160, 2013). "This decline in albumin level diminishes its protective functions—including improving endothelial dysfunction, regulating vascular tone, inhibiting platelet aggregation, and maintaining endothelial permeability—thereby markedly increasing the risk of PE progression and adverse clinical outcomes." (PMID 41608662, 2026). "Endothelial dysfunction also showed increased permeability to albumin." (PMID 40421989, 2025). "A decrease in albumin levels leads to endothelial dysfunction and a rise in inflammatory cytokines." (PMID 41008697, 2025). "Additionally, low serum albumin levels are known to exacerbate endothelial dysfunction and neuroinflammation, potentially explaining the stronger association between the CONUT score and clinical outcomes following MT." (PMID 40722296, 2025).
endothelial dysfunction (continued). "In our population, its inverse relationship with serum albumin might be a reflection of the degree of proteinuria and endothelial dysfunction." (PMID 41194165, 2025). "However, our findings remained unchanged after adjusting for low-grade inflammation, a fibrotic marker; and urinary albumin-creatinine ratio, which serves as a marker of endothelial dysfunction, in model." (PMID 40485703, 2025). "Low albumin levels may permit increased vascular permeability, decreased ability to scavenge reactive oxygen species, endothelial dysfunction and decreased anticoagulant and antiplatelet capacity." (PMID 40630165, 2025). "High blood glucose can stimulate the production of reactive oxygen species through plasma albumin, induce endothelial dysfunction, promote systemic inflammation, increase the number of activated microglia, and trigger neuroinflammation, thereby affecting cognitive and memory functions." (PMID 40556904, 2025). "We investigated whether initial resuscitation with different types of plasma or albumin decreases endothelial dysfunction and organ injury in a pneumosepsis rat model compared to the same volume of crystalloids." (PMID 37728777, 2023). "Alternatively, endothelial dysfunction might explain the observed link between urinary albumin excretion and other contributing factors." (PMID 37868453, 2023). "Flow-mediated vasodilation (FMD) as the marker for endothelial dysfunction was significantly impaired in the patients with elevated urinary albumin excretion compared to normoalbuminuric subjects, suggesting a significant association between endothelial dysfunction and albuminuria." (PMID 37367894, 2023). "Altered values of Doppler-derived CFR assessed with the Flowire (Philips Volcano, San Diego, CA, USA) have been correlated with markers of endothelial dysfunction, such as the albumin-to-creatinine ratio and subendocardial viability ratio, in hypertensive patients." (PMID 37510979, 2023). "At the glomerular level, hyperfiltration, endothelial dysfunction, thickened basement membrane, podocyte’s effacement/effusion and detachment, glomerular sclerosis and hyalinosis may all increase albumin leak at the glomerular apparatus." (PMID 36139492, 2022). "Additionally, albumin has antioxidant properties that aid in scavenging oxygen free radicals in plasma, and reductions in albumin levels increase blood viscosity, resulting in endothelial dysfunction." (PMID 36568875, 2022). "Decreased albumin levels can increase blood viscosity and endothelial dysfunction, which may contribute to PC-AKI development." (PMID 36568875, 2022). "In addition, endothelial dysfunction, inflammation, elevated glomerular pressure, or atherosclerosis contribute to increased albumin excretion [55•, 84, 85]." (PMID 36166185, 2022). "The RCTs included in our systematic review were not primarily designed to show an effect on CIMT, but on markers of endothelial dysfunction (flow-mediated dilation), insulin sensitivity (steady-state glucose infusion rate/insulin), or albuminuria (albumin-to-creatinine ratio)." (PMID 36992735, 2022). "In human umbilical vascular endothelial cells, human glycated albumin differentially regulates proteins involved in endothelial dysfunction, namely related to apoptosis and oxidative stress and the NF-KB cascade downstream to AGE-RAGE signaling, which can be counteracted by soluble RAGE." (PMID 34684632, 2021). "The Steno hypothesis explains the albumin leakage as a result of widespread vascular damage and endothelial dysfunction." (PMID 34574057, 2021). "Urine albumin-creatinine ratio (UACR) is a measure of renal microvascular endothelial dysfunction." (PMID 34570768, 2021).
endothelial dysfunction (continued). "The first indirect evidence of the role of non-oncotic properties derives from the observation that, in patients with SBP, the increase in arterial pressure is mediated, at least in part, by the improvement in endothelial dysfunction following albumin administration [46•], as previously discussed." (PMID 32837825, 2020). "It was proposed that albumin might function in suppressing vascular oxidative stress and preventing endothelial dysfunction." (PMID 31900124, 2020). "Recently, the endothelial dysfunction and plasma leakage had been identified in SFTSV infection and most viral hemorrhagic fever, manifested by fluid loss from the vascular compartment and by decreased level of ALB." (PMID 31136581, 2019). "Ponatinib increased plasma E-selectin and urinary albumin:creatinin in some animals, suggesting endothelial activation and potential endothelial dysfunction, wherein aberrant angiogenesis might be involved." (PMID 29946549, 2018). "As an important early feature of the atherogenic process, endothelial dysfunction could therefore result in increased urinary albumin excretion." (PMID 25500578, 2014). "The authors postulated that the association of increased albumin leakage with inflammation is only consequence of the availability of an increased number of large pores and is not related to endothelial dysfunction or CVD." (PMID 23418538, 2013). "Furthermore, the ability of albumin-coated microbubbles to adhere to vascular regions with glycocalix damage or endothelial dysfunction is another possible mechanism to deliver drugs even in the absence of ultrasound." (PMID 15546496, 2004). "This relationship may be explained by albumin’s role in countering oxidative stress, mitigating endothelial dysfunction, and reducing vascular permeability—key mechanisms that, when compromised, can exacerbate edema, neuronal injury, and overall disease severity." (PMID 41170336, 2025). "However, the persistence of this inflammatory state may reduce serum albumin levels leading to an enhanced oxidative stress responsible for endothelial dysfunction, platelet aggregation, and clot initiation." (PMID 38323429, 2024). "Furthermore, lower albumin levels may reflect endothelial dysfunction, a key factor in both cardiovascular health and MetS development, thus potentially explaining part of the relationship between LE8 score and MetS risk." (PMID 39480760, 2024). "In addition, a higher plasma albumin level could inhibit platelet activation and aggregation, and a decreased albumin level could adversely affect blood viscosity and give rise to endothelial dysfunction." (PMID 37932710, 2023). "This controversial finding could be explained as an increase of their catabolism or removal from the blood into the tissues during advanced inflammatory states and severe endothelial dysfunction in arteriosclerosis in the form of modified lipoprotein or albumin." (PMID 35371012, 2022). "Prior work in a study of 1567 subjects demonstrated major cardiac risk factors as independent correlates of urinary albumin excretion rate and prevalence of microalbuminuria in non-diabetic middle-aged men and women, suggesting that endothelial dysfunction is systemic." (PMID 34570768, 2021). "Therefore, it is possible that changes in endothelial function in the kidneys leading to leakage of albumin to the urine may serve as a marker for generalized endothelial dysfunction." (PMID 32359353, 2020). "The increase in urinary albumin excretion is likely to reflect not only glomerular damage but also systemic endothelial dysfunction and is consistent with the hypothesis that vasopressin induces urinary albumin excretion as previously reported in rats and humans." (PMID 30800291, 2019). "Furthermore, frequent daily postprandial states of relatively higher glucose levels could increase oxidative stress on the vessels leading to increased urinary albumin excretion secondary to endothelial dysfunction." (PMID 29505614, 2018).